IGF1 (insulin like growth factor 1)
Diseases named in the same sentence as IGF1 in open-access papers (continued):
Sharing a sentence is not in itself a finding about the gene and the disease.
colorectal cancer (continued). "Further research is recommended to investigate if circulating IGF1 and IGFBP3 levels can be used to identify people at high risk of colorectal cancer and to explore potential lifestyle or pharmaceutical ways to lower IGF1 bioactivity as a risk reduction strategy targeting high-risk individuals." (PMID 34858769, 2021). "Statistically significant association was detected between short IGF1 CA repeats and increased risk for colorectal cancer in hereditary non-polyposis colorectal cancer." (PMID 34178997, 2021). "However, other recent articles describe let-7 directly targeting Igf-1 and/or Igf-1 receptor in human colorectal cancer cell proliferation in endometrial stromal cells and in cultured testicular fragments." (PMID 34489723, 2021). "IGF1 expression is predominant in cancerous tissues like glioma and colorectal cancers." (PMID 34592879, 2021). "Although we did not identify a significant association between plasma IGF-1 concentrations and colorectal cancer risk, the limited power of this analysis means that we cannot rule out small-to-moderate effect sizes." (PMID 31668584, 2020). "In summary, in in vivo and cultured cell studies of colorectal cancer, expression of all of the IGF1 mRNA isoforms was confirmed, with advantage of isoform IGF1Ea over IGF1Eb and IGF1Ec when it comes to percentage, but similar quantitative expression of both IGF1Ea and IGF1Eb isoforms." (PMID 32977489, 2020). "Our finding for colorectal cancer confirm those of a previous MR study which showed an OR of colorectal cancer of 1.08 (95% CI 1.03‐1.12) per one SD increment of genetically‐predicted IGF‐1 levels." (PMID 32717139, 2020). "Further, IFITM2 was significantly up-regulated and induced after activation of beta-catenin signaling in colorectal cancers, and it was also reported to promote gastric cancer growth and metastasis through the insulin-like growth factor (IGF1)/IGF1 receptor (IGF1R)/STAT3 signaling pathway." (PMID 32765489, 2020). "In this MR analysis assessing the potential causal relation between serum IGF‐1 levels and several cancers, we found some evidence that increased IGF‐1 levels may increase the risk of colorectal cancer." (PMID 32717139, 2020). "For example, IGF1 could increase cell migration, invasion, and survival of colorectal cancer cells via the AKT pathway." (PMID 32851683, 2020). "Thus, targeting the IGF-1R/IGF-1 signaling pathway can be considered as an effective approach to both colorectal cancer prevention and treatment." (PMID 30987250, 2019). "The epidemiological data on IGF‐1 and colorectal cancer is supported by laboratory evidence." (PMID 27734632, 2016). "Although the etiology of IGF‐1 in second primary colorectal cancer is unknown, based on findings from normal colonic tissues, we can speculate about the potential complexity of this carcinogenic mechanism." (PMID 27734632, 2016). "Moreover investigation in SNP in IGF-1 and IGFR-1 indicate that IGF1-pathway polymorphisms are potential prognostic molecular markers in colorectal cancer and pancreatic cancer." (PMID 27405474, 2016). "A similar relationship between serum C-peptide levels (a marker for insulin production) and colorectal cancer risk was reported in the Physicians' Health Study, and this association was independent of IGF-1 and IGFBP-3 levels." (PMID 23304125, 2012). "As such, agents targeting IGF-1 are currently under development for the treatment of colorectal cancer, and perhaps could be used in combination with anti-MCH treatments." (PMID 22848656, 2012). "Both insulin and IGF-1 are potent mitogens that promote colorectal cancer cell growth and survival in vitro, and elevated blood levels of IGF-1 and insulin are associated with increased risk of developing colorectal cancer." (PMID 21081932, 2011).
colorectal cancer (continued). "High circulating levels of IGF-1 and low levels of IGFBP-3 (a major IGFBP that accounts for ~75% of IGF-1 bound) have been shown to be associated with an increased risk of several types of cancers, including colorectal cancer." (PMID 18976499, 2008). "Monensin could suppressed IGF1R expression via increasing IGF1 in colorectal cancer cells." (PMID 36896461, 2023). "Mitogenic and anti-apoptotic activity of mature IGF-1, as well as different transcripts and precursor IGF-1 peptides, qualify IGF-1 to the group of growth factors implicated in the initiation and progression of various cancers, including colorectal cancer (CRC)." (PMID 34208601, 2021). "In a supplementary analysis using data from a genome‐wide association study in a Japanese population, genetically predicted IGF‐1 levels were statistically significantly associated with colorectal cancer but not prostate, lung, esophageal, stomach, or liver cancer." (PMID 32717139, 2020). "Intriguingly, 3 of the genes (IGF1, PIK3R1, and CDH2) of the 10 were targets of miR-221/222-3p, indicating that miR-221-3p and miR-222-3p play undeniable roles in colorectal cancer." (PMID 41602427, 2026). "Based on TCGA database analysis, We discovered that the expressions of IGF-1, IGF1R and RAGE in colorectal cancer tissues were different from those in normal tissues." (PMID 36890832, 2023). "We found that the expressions of IGF-1, IGF1R and RAGE in colorectal cancer tissues were different from those in normal tissues." (PMID 36890832, 2023). "IGF-1/IGF-1R and miR-let-7e have been previously reported to downregulate each other and modulate proliferation and migration in colorectal cancer cells." (PMID 36062186, 2022). "A review summarized ACEI/ARB presented a potential effect in colorectal cancer by inhibiting vascular endothelial growth factor and insulin-like growth factor 1, and the usage of ACEI suppressed the development and metastasis of colorectal cancer." (PMID 35087400, 2021). "In colorectal cancer, HOXA13 overexpression mediated by insulin-like growth factor 1 promotes metastasis through upregulating downstream targets ATP-citrate lyase and insulin-like growth factor 1 receptor." (PMID 34722321, 2021). "There has not been a comprehensive examination of regulation of lncRNAs by IGF1, but IGF/Insulin signaling represses the expression of CRNDE30, a lncRNA highly expressed in colorectal cancer and gliomas." (PMID 32444795, 2020). "In fact, the expression of IGF-1 and IGF-1 receptor increases with tumor size in colorectal cancer in a human study." (PMID 32709256, 2020). "The expression levels of IGF1 and IGF-1R were increased in colorectal carcinomas, compared with normal colonic mucosa." (PMID 32486076, 2020). "For example, curcumin has been shown to downregulate IGF-1R and INSR in colorectal cancer cells, and to block IGF-induced activation of IGF-1R, PI3K-AKT and mTOR, suppressing carcinogen-driven skin tumorigenesis in an Igf-1 driven model." (PMID 31416218, 2019). "Inhibiting IGF-1 and IGF-1R signalling has shown promising results in colorectal cancer by blocking the influence of its microenvironment." (PMID 31076571, 2019). "Whereas in colorectal carcinoma, the local expression levels of total IGF-1 mRNA and all splicing isoforms of IGF-1 mRNA were decreased as compared to normal colon tissues." (PMID 25333772, 2014). "In colorectal cancer cells, APN promotes cell survival during glucose deprivation by AMPKα and PPARα activation and IGF-1/PI3k/Akt/mTOR pathway inhibition." (PMID 23894332, 2013). "In a case–control study, it was observed that serum IGF-1 values were significantly higher in patients with colorectal cancer, than in subjects without colorectal cancer." (PMID 40088375, 2025). "Studies have shown that LUNAR1 inhibition significantly suppresses IGF1 signaling in CRC, and LUNAR1 may be a promising prognostic marker for clinical management of colorectal cancer." (PMID 39830506, 2024).
colorectal cancer (continued). "In our further survival analysis of patients with TCGA colorectal cancer demonstrated that tumor expression of IGF-1R and RAGE was associated with shorter overall survival (Figure, P=0.018;Figure,P=0.013) while IGF-1 was not correlated with the prognosis." (PMID 36890832, 2023). "In addition, it has been demonstrated that the insulin-like growth factor 1 (IGF1) and IGF1 receptor (IGF-1R) overexpression in colonic mucosae leads to Src activation that supports the proliferation of human colorectal carcinoma cell lines." (PMID 37760840, 2023). "Therefore, in parallel to analyses of IGF-1R, IGF-1/2 and MMP-7 mRNA expression in tissue from colorectal cancer patients, we assessed the effects of the IGF-1R-inhibitory compound PPP in four colon carcinoma cell lines." (PMID 22159423, 2012). "Our findings also suggest that among those with low plasma 25(OH)D levels, having either high IGF-1/IGFBP-3 ratio or high C-peptide levels increased risk, but being high in both did not further increase colorectal cancer risk appreciably." (PMID 22216097, 2011). "IGF-1, IGF-2 and IGFBP-3 were measured in the serum of 135 men who developed colorectal cancer over 12 years of follow-up and 661 control subjects drawn from the cohort, who were matched to the index cases by neighbourhood of residence, age, and year and month of sample collection." (PMID 11742490, 2001). "Researchers in one small randomised controlled trial (RCT) reported effects of post-operative physical activity on the IGF axis with a significant increase in IGF-1 and IGFBP-3 in stages II–III colorectal cancer survivors, which could be of benefit for the patient." (PMID 28482864, 2017). "Igf-1 expression between normal and cancerous tissues and cells was evaluated by Kasprzak and co-workers and a downshift of the Igf-1b content in the favor of Igf-1a isoform was reported when colorectal cancer cells and non-tumor tissue were analyzed." (PMID 25018100, 2014). "Interestingly, the hypothesis of IGF-I as modifier of disease risk is supported by a recent report showing a strong association of IGF1 CA repeat polymorphism and early onset of colorectal cancer in hereditary non-polyposis colorectal cancer patients." (PMID 20214787, 2010). "Other proteins, including TIMP-2, IGF-1, and HIF-1α, demonstrate increased expression in clones of peritoneal metastasis from colorectal cancer as opposed to primary colorectal tumors or liver metastases originating from colorectal cancer." (PMID 37689664, 2023).
malnutrition (176 papers, 2006 to 2026). Inadequate nutrition resulting from poor diet, malabsorption, or abnormal nutrient distribution. "Malnutrition can independently cause alterations in the GH-IGF1 axis, leading to both GH insufficiency and IGF-1 resistance." (PMID 40275257, 2025). "Second, chronic low albumin levels indicate prolonged protein deficiency and malnutrition, which can weaken bone formation by reducing collagen production and IGF-1 availability – key factors for bone strength." (PMID 40297171, 2025). "A comprehensive blood panel is necessary to assess thyroid function, insulin-like growth factor-1 (IGF-1), and coagulation factors, given the increased risk of nutritional deficiencies and hematological disorders." (PMID 40564888, 2025). "Under conditions of nutritional deficiency, children experience a reduction in glucose levels, which leads to the decreased secretion of insulin and IGF-1 in the body." (PMID 40362802, 2025). "Lower IGF-1 levels have been associated with various pathologies, chronic diseases, inflammation, and malnutrition." (PMID 38612456, 2024). "The present study used IGF-1 as a growth biomarker in stunting since it was more sensitive to nutritional deficiency than another biomarker, namely IGF Binding Protein 3 (IGFBP3)." (PMID 37946290, 2023). "Lower levels of prealbumin, transferrin, IGF-1 and leptin are known to be associated with malnutrition and as expected, levels of these markers increased following nutritional intervention." (PMID 35334853, 2022). "Previous data showed that in older patients, extracerebellar MRI lesions were accompanied by deficiency of the GH/IGF-1 axis, malnutrition, and high ataxia scores." (PMID 33893614, 2022). "Although pediatric CD patients have normal growth hormone (GH) concentrations, low serum insulin-like growth factor-1 (IGF-1) levels caused by malnutrition and elevated proinflammatory cytokine levels contribute to growth impairment." (PMID 33446154, 2021). "Previous studies have observed the significant increase of muscle mass in mice with over-expression of IGF-1 and also revealed the decrease of IGF-1 in mice with attenuated muscle mass caused by malnutrition, diseases or aging." (PMID 32256674, 2020). "Pathological conditions such as malnutrition, severe disease, sepsis, high-dose exogenous glucocorticoid use, and inflammation are significantly associated with low levels of IGF-1 mRNA in the muscle." (PMID 32264885, 2020). "Previous studies demonstrated that IGF-1 administration effectively attenuates the inhibition of protein synthesis during malnutrition and ameliorates the loss of muscle mass." (PMID 25909895, 2015). "In both cohorts, low CNDP1 levels were associated with markers of poor prognosis including weight loss, malnutrition, lipid breakdown, low circulating albumin/IGF1 levels and poor quality of life." (PMID 25898255, 2015). "Plasma IGF-1 levels have been used as a potential measure of nutritional status and ‘anabolic responsiveness’ and the association exists such that during malnutrition IGF-1 reduces and during nutritional excess increases in proportionality." (PMID 22537670, 2012). "Since malnutrition which referred to deficiencies in energy or nutrient uptake commonly caused growth retardation, we tested expression levels of hepatic Fgf21 and Sirt1, key genes for Igf1 inhibition under malnutrition condition." (PMID 40598150, 2025). "Malnutrition in neonatal rats causes reductions in systemic IGF1 and 2 and elevation of IGFBP250." (PMID 41315420, 2025). "However, low IGF-1 levels are linked to nutritional deficiency such as in patients with eating disorders with levels returning to normal upon weight restoration." (PMID 37386483, 2023). "Additionally, malnutrition has been linked to decreasing IGF1 expression in liver tissue, which is reflected by the significantly lower expression under P-Ca+ compared to P-Ca- in liver tissue of the LB strain in this study." (PMID 35749523, 2022).
malnutrition (continued). "IGF-1 deficiency in cirrhotic patients may be related to hepatocellular dysfunction, malnutrition, oxidative damage, altered lipid metabolism, and insulin resistance." (PMID 36374927, 2022). "Whereas, decreased IGF-1 levels were associated with various pathological conditions, including chronic diseases, such as muscle dystrophy, rheumatoid arthritis (RA), inflammation, and malnutrition." (PMID 35012004, 2022). "Moreover, secondary insulin growth factor-1 (IGF-1) deficiency due to malnutrition can result in loss of oligodendrocyte proliferation and differentiation, inhibition of myelination and eventually brain volume reduction." (PMID 33673193, 2021). "These causes (and in particular malnutrition) may also explain - in part - the IGF1 findings in our patients." (PMID 34220703, 2021). "The effect of GH and IGF-1 therapy on bone osteoporosis and fracture healing is mediated by many factors that can realize a GH resistance: inflammatory cytokines, sex hormones levels, nutritional deficiency, and muscle mass and strength." (PMID 25147565, 2014). "Secondary deficiency of IGF-1 can be caused by malnutrition or hypothyroidism." (PMID 23305374, 2013). "IGF-1 dosage is the first biochemical screening test for GH deficiency, even if its result is altered also for other reasons, such as hepatopathy (due to both iron accumulation and hepatitis viruses), chronic anemia, increase in inflammatory cytokines, malnutrition and GH resistance." (PMID 35407442, 2022). "The less energy expenditure could be due to a consequence of a lower increase in lean body mass, or other mechanisms, such as, decreased IGF-1 levels and a higher ratio of cortisol to insulin associated with malnutrition, acting in favour of conservation of energy and/or body fat." (PMID 29965973, 2018). "Although IGF-1 levels can be influenced by various factors (such as malnutrition, pubertal stage, and age), it is clear that they are highly dependent on GH secretion." (PMID 41169468, 2025). "Synthesis and release of GH and IGF-1 are closely influenced by the nutritional status of animals, with malnutrition shown to decrease serum IGF-1 and GH levels." (PMID 40218302, 2025). "These musculoskeletal complications result from various mechanisms, including chronic inflammation, malnutrition, hypogonadism, reduced IGF-1 synthesis, and immobility." (PMID 41458554, 2025). "Third, low muscle mass is related to many factors in older adults, such as cellular senescence, immobility, malnutrition, neurological denervation, atrophy of the muscle fibers, decreased IGF-1, inflammaging, atherosclerosis, chronic diseases, and drugs." (PMID 40005003, 2025). "Nutritional deficiency can significantly disrupt the chronobiology (daily rhythmic patterns) of IGF-1 by reducing IGF-1 production, disrupting the growth hormone–IGF-1 axis, altering circadian regulation, and having consequences for growth and development." (PMID 40362802, 2025). "The pathogenesis of growth failure in celiac disease covers malnutrition itself, but it seems to be also related to the dysregulation of GH/IGF-1 axis." (PMID 39200139, 2024). "Numerous studies have shown that malnutrition alters the GH/IGF-1 axis and the response of growth plate to GH and IGF-1." (PMID 39107621, 2024). "Studies in children with protein-calorie malnutrition have demonstrated elevated GH levels and low IGF-1 levels which are normalized after adequate protein intake is met." (PMID 39062266, 2024). "During malnutrition, SIRT1 blocks GH signal transduction in hepatocytes to reduce the IGF-1 secretion and prevent hypoglycemia (i.e., it causes transient GH resistance)." (PMID 37895086, 2023). "A concern has been raised due to the low concentration of free IGF-1 serum in several catabolic conditions such as malnutrition, anorexia nervosa, and poorly controlled type 1 diabetes, as well as in hypothyroidism." (PMID 37946290, 2023).